BRCA1 (BRCA1 DNA repair associated)
Diseases named in the same sentence as BRCA1 in open-access papers (continued):
Sharing a sentence is not in itself a finding about the gene and the disease.
tumor (continued). "For example, in TNBC, hypermethylation of CpG islands within the promoter regions of tumor suppressor genes, such as BRCA1 and PTEN, leads to their transcriptional silencing contributing to tumor initiation and progression." (PMID 39744000, 2024). "BRCA1- and BRCA2-altered tumours have shown enhanced immunosurveillance in several preclinical studies, but a correlation between ICB treatment and patient outcome was not evident." (PMID 39271762, 2024). "BRCA1, BRCA2, and RAD51 are all key participants in DNA damage repair and show a promoting role in tumor metastasis." (PMID 38983866, 2024). "BRCA1 or BRCA2 PVs have been reported in 15−22% of HGSOC, and more than 70% of these tumours are grade 3 carcinomas." (PMID 38443545, 2024). "Univariate logistic regression further revealed that BRCA1 overexpression was more likely in LUAD patients ≤65 years of age and with advanced tumor stage, lymph node involvement, metastasis, or advanced stage." (PMID 38090061, 2023). "Normally, BRCA1 can inhibit the activity of VEGF and reduce its secretion to impede tumor growth, invasion, and metastasis." (PMID 37114130, 2023). "As previously discussed, BRCA1 negatively regulates IGF-I, and its defectiveness keeps always active the IGF-I/PI3K-Akt pathway, which significantly promotes tumor cell survival and proliferation." (PMID 37081976, 2023). "Results from our analysis also indicate that, among the thirty genes which are differentially expressed in OSCCs, seven of them (namely BRCA1, CCNE2, CDC25C, CDK1, CDK2, E2F1, and FANCD2) positively correlate with both tumor grade and HPV infection." (PMID 36768994, 2023). "To make a binary call on the HRD status of a tumor (i.e., HRD-positive vs. HRD-negative), we aimed to identify a threshold of HRD score that can effectively separate BRCA1/2 BILOF from the others." (PMID 37258600, 2023). "BRCA1 and BRCA2 are required for mammalian development, and they function as tumor suppressors to support the maintenance of genomic integrity." (PMID 37813891, 2023). "PPAR-ɣ regulates lipid and glucose metabolisms, supports tumor growth through induction of apoptosis of T cells, and modulates the expression of tumor suppressor genes, such as PTEN and BRCA1." (PMID 37760840, 2023). "Studies have shown that BRCA1 and BRCA2 help repair the DSBs, initiate HR, and maintain genomic integrity, providing tumor-suppressing effects." (PMID 37509303, 2023). "Importantly, tumours associated with germline PVs in BRCA1 (gBRCA1m) tend to have higher histologic grades and are more likely to yield triple-negative tumours (58.1%) compared to tumours associated with germline PVs in BRCA2 (gBRCA2m) and noncarriers (34.4% and 7.5%, respectively)." (PMID 38414963, 2023). "The BRCA1 and BRCA2 proteins have essential physiological roles in maintaining genome stability in rapidly proliferating tumor cells, not only by promoting DSB-repair via HR but also by facilitating DNA replication." (PMID 37834403, 2023).
tumor (continued). "Regarding TNBCs and ER < 10% tumors with concordant tumor and WBC BRCA1 methylation, 11 out of 14 were basal-like, two were normal-like, while one tumor expressed a HER2-enriched profile, despite absence of HER2 gene amplification or positive protein staining." (PMID 38053165, 2023). "Following the approval of therapies targeting homologous recombination defects (HRD) in several cancer settings, tumour testing for the Hereditary Breast and Ovarian Cancer Syndrome (HBOC) genes BRCA1 and BRCA2 has rapidly spread." (PMID 37179432, 2023). "Preliminary studies suggested HGSOC patients with BRCA1 mutations demonstrated higher CD8+ TILs, and neoantigen load might explain higher CD8+ TILs, which is consistent with patients with low TMErisk scores exhibiting more neoantigens and an increased number of tumor-infiltrating lymphocytes." (PMID 37090728, 2023). "In primary tumor tissue samples, the greatest changes in expression are mainly in AF050 and AF069 patients who have wild-type BRCA1/2." (PMID 37240218, 2023). "We first evidenced a larger number of circRNAs in BRCA1 than in BRCA2, in accordance with RJunBase, with a similar qualitative repertoire between normal and tumor tissues." (PMID 37046838, 2023). "Secondly, we have demonstrated a disequilibrium for BRCA1 and BRCA2 in the circRNA/mRNA ratio between the tumor and normal breast tissues." (PMID 37046838, 2023). "Significant SNV alterations were observed in BRCA2, ACACB, BRCA1, MSH6 and IFI16 in most tumour types." (PMID 37660060, 2023). "Substantial CNV deletions were observed in PABPC5, MSH6, IFI16, GNS, ERCC4, BRCA1 and ACACB, while substantial CNV amplification was observed in most tumour types for the remaining genes." (PMID 37660060, 2023). "BRCA1 and BRCA2 are often mentioned together, partly owing to their tumor-suppressor activities and roles in HR repair." (PMID 37209095, 2023). "The most investigated gene-specific methylation biomarkers were RASSF1A, BRCA1, and OPCML, all being tumor-suppressor genes previously reported to be involved in tumorigenesis and methylated in multiple solid cancers." (PMID 36788585, 2023). "Consistent with the INPP4B tumor suppressor function, the tumorigenic markers MAPK, SRC, and SNAI2 were elevated, and the tumor suppressor proteins RB1, BRCA1, and CHEK2 were decreased in the cells treated with siRNA targeting INPP4B." (PMID 38001678, 2023). "It is plausible that sequential administration of a potent PARPi like talazoparib in combination with carboplatin can enhance primary tumour and metastasis inhibition in BRCAMUT and BRCA1/2 wild-type (BRCAWT) TNBCs, and decrease toxicity." (PMID 36941406, 2023). "We found concordant tumor and mosaic WBC BRCA1 epimutations in 10 out of 66 patients with TNBC and in four out of six patients with estrogen receptor (ER)-low expression (< 10%) tumors (combined: 14 out of 72; 19.4%; 95% CI 11.1–30.5)." (PMID 38053165, 2023). "The most investigated genes were RASSF1A, BRCA1, OPCML, APC, HIC1, and HOXA9, all being tumor-suppressor genes." (PMID 36788585, 2023). "Tumor growth was monitored after treatment end in 3 PDX, 2 BRCA1-Me TNBC (b3977, b4122) and 1 BRCA1-Mut HGSOC (o10047) Both BRCA1-Me TNBC resumed growth shortly after end of olaparib administration." (PMID 37007122, 2023). "We have characterized novel BRCA1 and BRCA2 circular RNAs and, for the first time, described a disequilibrium in circRNA/mRNA levels between tumor and normal breast tissues." (PMID 37046838, 2023).
tumor (continued). "BRCA1 and BRCA2 act as tumor suppressor genes as they are key regulators of DNA repair through homologous recombination." (PMID 38203374, 2023). "Notably, this form of HUWE1-mediated resistance appeared to be particular to tumour cells with BRCA1 exon 11 truncating mutations that are able to express the BRCA1-∆11q protein and was not seen, for example, in tumour cells with BRCA1 exon 22 mutations or in BRCA2 mutant cells." (PMID 37491606, 2023). "BRCA1 and BRCA2, two tumor suppressor genes that interact with G4 structures, participate in homologous recombination and thus allow the repair of DNA DSBs." (PMID 36770824, 2023). "Similarly, in our cohort, BRCA1/2 mutations were present in tumors without PARPi approval, such as endometrial, lung, colon, and biliary tract tumors, as well as in the case of a tumor of unknown primary origin." (PMID 37761329, 2023). "Selective autophagy cargo receptor neighbor of BRCA1 (NBR1) acts a key factor of autophagy-mediated focal adhesion turnover, thereby enhancing tumor migration." (PMID 36831455, 2023). "In the BRCA1(−) tumor model, CTLA4 blockades combined with PARPi induce protective anti-tumor immunity and significant survival benefit by locally inducing anti-tumor immunity and increasing levels of IFNγ." (PMID 36900418, 2023). "The percentages of proliferating tumor cells positive for RAD51 and BRCA1 foci were evaluated using an immunofluorescence assay, as a readout of homologous recombination repair status." (PMID 37686585, 2023). "By inhibiting angiogenesis, antiangiogenic agents induce hypoxia in the tumor microenvironment and downregulate the key factors involved in HRR, such as BRCA1/2 and Rad51." (PMID 38021157, 2023). "BRCA1 and BRCA2 as tumour suppression genes are crucial in the DNA repair process by homologous recombination, which plays an essential role in chromosome integrity." (PMID 37644384, 2023). "The tumor volume, weight and tumor inhibition rate in BRCA1 + NP and BRCA2 + NP treatment groups were significantly lowered, indicating role of wild type BRCA1 and BRCA2 in the tumor microenvironment." (PMID 36631481, 2023). "However, unlike other tumor types, PCa genomes rarely contain BRCA1/2 mutations." (PMID 37629155, 2023). "Grouping the TNBC and ER-low (1–9%) tumors together, concordant tumor and WBC BRCA1 methylation was observed in 14 out of 72 patients (19.1%; 95% CI 11.1–30.5%)." (PMID 38053165, 2023). "At the next stage of the work, in the formed sample of patients, using the Accel-Amplicon BRCA1, BRCA2, and PALB2 panel, tumor samples were screened before and after chemotherapy for the presence of mutations in the studied genes." (PMID 37628606, 2023). "Human genes called BRCA1 and BRCA2 translate into tumor suppressors, which contribute to DNA repair as well as aid in preserving the integrity of the genomic information." (PMID 36971312, 2023). "Germline and somatic alterations in BRCA1/2 were the primary criterion, alterations in other HRR genes were the secondary criterion for tumor classification with respect to HRR status." (PMID 35681079, 2022). "Being a tumor suppressor, it is interesting that HPV E6 and E7 would promote BRCA1 expression, but remarkably, these viral oncoproteins have evolved a mechanism to bind and functionally inactivate BRCA1 although they do not proteolytically degrade it." (PMID 36016386, 2022). "BAP1 was initially shown to localize to the nucleus where its primary interaction was binding to BRCA1 and enhancing its tumor suppressive activity 5, and subsequent researches have revealed that BAP1 acts independently as a tumor suppressor." (PMID 34976173, 2022). "BRCA1 and BRCA2 are tumor-suppressor genes involved in transcriptional regulation and are critical to the repair of DSBs in the DNA molecule, playing a key role in the HR pathway." (PMID 35740437, 2022).
tumor (continued). "Although BRCA1 requires BARD1 for stability and tumor suppressor functions, BARD1 also plays distinct roles in cell cycle progression." (PMID 35084436, 2022). "BRCA1 and BRCA2 are known as tumor-suppressor genes that function to limit inappropriate cell growth and signal cell death when needed." (PMID 35626055, 2022). "A study of tumor xenografts from TNBC patients revealed a novel resistance mechanism in BRCA1-methylated PDX (patient-derived xenograft) tumors." (PMID 35300412, 2022). "Tumor cells (MB231 and BRCA1−/−) and normal healthy cells (MCF10A) in dataset GSE171957 were considered." (PMID 35265522, 2022). "It is established that BRCA1’s role in HR-mediated DNA DSB repair is important in the maintenance of genomic stability and tumor suppression." (PMID 36346676, 2022). "BRCA1 and BRCA2 are tumour suppressor genes that play a critical role in maintaining genomic stability via the DNA repair mechanism." (PMID 35729312, 2022). "Here, we examined the impact of tumor-specific thresholds and measurement of promoter methylation of BRCA1 and RAD51C on unexplained proportions of HRD cases across various tumor types." (PMID 35783256, 2022). "Four of these patients (11.8%) carried a possible germline PV/LPV detected in the BRCA1, RAD51C, BRIP1, or PTEN gene in the tumor sample." (PMID 35326583, 2022). "PARPi showed improvement in tumor drug response, OS and PFS for patients with locally advanced or metastatic HER2-negative BC with BRCA1/2 germline variation, thus supporting the use of PARPi in BC patient care." (PMID 36140723, 2022). "PPA was highest in samples with a tumor fraction of >10%, especially for potentially actionable alterations in PIK3CA (93%) and BRCA1/2 (95%)." (PMID 36470901, 2022). "Our data to this point revealed that BRCA1 mutation in mammary epithelial cells could cause oncogenic activation through the S100A9-CXCL12 axis in the mammary epithelium, promote signaling through immune cells, and induce the formation of a tumor-permissive microenvironment." (PMID 35304461, 2022). "BRCA1 and BRCA2 are tumor suppressors that maintain genomic DNA stability by promoting double-strand DNA break (DSB) repair via homologous recombination and non-homologous end-joining (NHEJ)." (PMID 36140723, 2022). "BRCA1 and BRCA2 are the most recognized tumor-suppressor genes involved in double-strand DNA break repair through the homologous recombination (HR) system." (PMID 35740616, 2022). "Three additional HRD tumors harbored VUSes, of which tumor M106 was found HRD by two tests (RECAP and BRCA1/2-like classifier) and M211 and M072 by one test only (RECAP, BRCA1/2-like classifier, respectively)." (PMID 35662281, 2022). "Among these genes, BRCA1, RB1, RBAK and CSMD3 are tumour suppressors, while TRRAP functions as an oncogene." (PMID 35735060, 2022). "Tumour genetic testing is particularly important for HGSOC, as 23–43% of BRCA1/2 PVs are somatic and would be missed by standard germline (i.e. blood) genetic testing." (PMID 35418215, 2022). "BReast CAncer gene 1 (BRCA1) and BRCA2 (BRCA1/2) are tumor-suppressor genes that play a key role in repair of double-strand DNA breaks via the conservative homologous recombination repair (HRR) process." (PMID 36224343, 2022). "It was reported that hypoxia repressed BRCA1 expression by compromising the function of E2F1, resulting in tumor progression." (PMID 35155430, 2022). "Among the BC patients positive for BRCA1-, three (100%) had a triple-negative BC whereas, among those positive for BRCA2- tumours, two were triple-negative BC (40%), one was Luminal B/HER2- (20%) and two were Luminal B/HER2+ (40%)." (PMID 35886069, 2022). "Upon BRCA1/2-depletion for 24 h, we observed increased numbers of CD8+ T cells that migrated towards the BT-549 tumor cells, which was decreased upon MYC overexpression." (PMID 36323660, 2022). "BRCA1 was also found to bind and stabilize hypoxia-inducible factor-1α (HIF-1α) and promote tumor survival." (PMID 35453307, 2022).
tumor (continued). "The superimposed deduction of BRCA1, RAD51 and PARP1 with both sc-13 and NU-7441 treatment indicated the two essential pathways critical for tumor cell replication and genome stability in response to replication stress." (PMID 35414100, 2022). "Nucleic acid tumor markers include BRCA1, BRCA2, microRNA, circulating tumor DNA (ctDNA), circulating cell-free DNA (ccfDNA), circulating RNA (circRNA), long noncoding RNAs(lncRNA), etc.." (PMID 35330093, 2022). "If tumor genotyping only was performed, 96.1% (49/51) PV/LPV in HBOC genes would be detected while 2 germline HBOC PV/LPV would be missed (1 × BRCA1, 1 × ATM)." (PMID 35326583, 2022). "Among the 74 tumor samples harboring VUS only, 36 (48.6%) cases had alterations in BRCA1, 37 (50%) tumors had VUS in BRCA2 and one case (1.4%) presented VUS in both BRCA1 and BRCA2 genes." (PMID 35406410, 2022). "To define differential PARP1 interacting proteins, we harnessed these olaparib and rucaparib analogs for chemical proteomics experiments with the BRCA1-isogenic UWB cell line pair and with OC patient tumor tissues that were collected prior to drug therapy." (PMID 36183837, 2022). "BRCA1 and BRCA2 genes are integral components of the HR repair pathway, acting as tumour suppressors and preserving the chromosome structure." (PMID 35805770, 2022). "One proposed hypothesis for the loss of BRCA1 methylation following chemotherapeutic treatment and the emergence of resistant tumor recurrences is the rapid expansion of a non-methylated subclone from a heterogeneous tumor cell population that contains BRCA1meth and nonBRCA clones." (PMID 35857626, 2022). "In our study, we tested tumor DNA by NGS with a small HR-gene panel, as well as BRCA1 and RAD51C promoter methylation." (PMID 36294734, 2022). "i)We do not treat patients depend on the phenotype of the tumor varies whether it is a BRCA1 (mainly TNBC) or a BRCA2 (mainly HR positive) mutations; ii) Adjuvant therapy is a standard systemic treatment and depends on tumor stage, grade, and molecular subtypes, but not gene mutation variants." (PMID 35494038, 2022). "The tumor from case 3 was most likely HRD, as indicated by the BRCA1 gene alteration and marked response to PARPi monotherapy." (PMID 34667258, 2021). "Paclitaxel (175 mg/m2) and Carboplatin AUC5 (every 3 weeks) was the most used combination whether as neoadjuvant (84.8% of respondents), adjuvant after PDS (84.8–78.8% of respondents) or after NACT and IDS (78.8–69.7% of respondents), regardless of tumour and/or germline BRCA1/2 mutations." (PMID 34768353, 2021). "Dimerisation of BRCA1 and BARD1 is required to stimulate their shared ubiquitination activity and is required for the heterodimer tumour suppressor functions." (PMID 33672422, 2021). "In standard culture conditions, ovarian commercial and tumor-derived cell lines showed different expression levels of PARG protein and noticeably, the BRCA1 protein was at a very low level in SNU251 cells." (PMID 34778062, 2021). "The BRCA1 and BRCA2 genes mediate repair of DNA double strand breaks and thus are termed tumour suppressor genes." (PMID 34209669, 2021). "The synergistic anti-tumor effects of olaparib and selinexor were also observed in mouse xenograft models of TNBC cell lines MDA-MB-468 (BRCA1-wt) and MDA-MB-436 (BRCA1-mut)." (PMID 34504648, 2021). "This implies that AURKB disruption leads to a decrease in cell proliferation and cytokinesis whereas disruption in BRCA1/BRCA2 resulted in abnormal cytokinesis, eventually, encouraging tumor progression." (PMID 33915740, 2021). "In germline BRCA1/BRCA2/RAD51C/RAD51D/BRIP1 PVs, 44.4% (24/54) had a positive FH compared to 11.3% (28/249) of sporadic tumours (p < 0.001)." (PMID 34503154, 2021).